TRIM71 (tripartite motif containing 71)
Diseases named in the same sentence as TRIM71 in open-access papers (continued):
Sharing a sentence is not in itself a finding about the gene and the disease.
cancer (16 papers, 2013 to 2024). A tumor composed of atypical neoplastic, often pleomorphic cells that invade other tissues. "LINK-A (LINC01139) acts as an oncogene by downregulating cancer cell antigen presentation via suppression of PKA-mediated phosphorylation of the E3 ubiquitin ligase TRIM71." (PMID 37346034, 2023). "Altogether, previous research on TRIM71 has been mostly focused on embryonic and neural stem cells as well as cancer cells." (PMID 34055789, 2021). "First, we found that TRIM71 is highly expressed in ovarian epithelial cells HOSE compared with cancer cells." (PMID 31570706, 2019). "Together, these results indicate that TRIM71 binds to the TA domain of mtp53s via its NHL domain in cancer cells." (PMID 31570706, 2019). "More importantly, future work should unveil the functional impact of the interaction between lncRNAs and TRIM71 in other biological contexts, including neural development, cancer, and reprogramming." (PMID 30911006, 2019). "TRIM71 expression is upregulated in several cancer types and has been correlated with advanced tumor stages and poor prognosis." (PMID 31732746, 2019). "Depletion of TRIM71 in these cancer cell lines clearly recapitulated the results obtained in our in vitro transformation assays as well as our in vivo tumorigenicity assays." (PMID 27821801, 2016). "siRNA-mediated TRIM71 knockdown increased the proliferation of both Caco-2 and Tera-1 human cancer cell lines compared with control siRNA-transfected cells." (PMID 27821801, 2016). "Second, we extended this analysis beyond primary cells, introducing siRNA specific for TRIM71 in the cancer cell lines Caco-2 and Tera-1, which express both TRIM71 and Lin28B as well as all components of the conserved signaling pathway." (PMID 27821801, 2016). "Interestingly, TRIM71 expression is downregulated in various cancer tissues in which the LIN28B–let-7–HMGA2 signaling pathway is conserved compared with normal tissue counterparts." (PMID 35806250, 2022). "Notably, we also showed that TRIM71 expression differs between cancer tissues and adjacent tissues, with overexpression observed in NSCLC cells." (PMID 29541383, 2018). "Moreover, we altered the expression of TRIM71 in NSCLC cell lines and evaluated changes in cancer-related phenotypes in these cells to determine the role of TRIM71 in NSCLC." (PMID 29541383, 2018). "First, we tested whether the TRIM71-Lin28B-let-7-HMGA2 signaling pathway operated in those cancer cell lines." (PMID 27821801, 2016). "Specific knockdown of TRIM71 expression increased cancer cell proliferation and invasion." (PMID 27821801, 2016). "Furthermore, a bioinformatics analysis revealed that TRIM71 expression was downregulated in various types of cancer tissue from patients." (PMID 27821801, 2016). "Moreover, we found that TRIM71 expression is severely downregulated in tumor tissues from various cancer patients." (PMID 27821801, 2016). "Furthermore, the specific knockdown of TRIM71 increased the proliferation of cancer cells." (PMID 35806250, 2022).
cancer (continued). "Thus, in contrast to previous studies, our findings suggested that TRIM71 may participate in different biological mechanisms in cancer cells than in embryos and embryonic stem cells." (PMID 29541383, 2018). "Similar to earlier findings in mES and EC cells, we showed that TRIM71 mediates CDKN1A mRNA regulation and controls proliferation of HEK293 and HepG2 cancer cells." (PMID 31732746, 2019). "TRIM71 expression was decreased in cancer tissue compared with normal tissue counterparts, including cancer tissues from the brain, breast, cervix, esophagus, head and neck, kidney, lung, ovary, prostate, stomach, and vulva." (PMID 27821801, 2016). "TRIM71 is the most-upstream post-transcriptional modulator in the Lin28B-let-7-HMGA2 oncogenic signaling pathway, and serves a pivotal role in tumor formation, tumorigenic progression, and malignancy of cancer." (PMID 27821801, 2016). "Low levels of let-7b and -c have been identified in different subtypes of AML, and the causal relationship of its deregulated expression in cancer can be supported by evidence suggesting it targets a number of genes involved in the cancer process such as KRAS, TRIM71, nRAS, MYC, and HMGA2." (PMID 24416592, 2013). "Thus, the contribution of TRIM71 to miRNA-mediated silencing as well as the functional relationship between TRIM71 and AGO2 with regard to the control of stem cell fate and cancer cell proliferation remain unclear." (PMID 31732746, 2019). "However, TRIM71 is unusual in that, unlike other cancer-related TRIM-NHL protein family, it has not previously been implicated as a tumor suppressor." (PMID 27821801, 2016). "Since Lin28B and HMGA2 are downstream post-transcriptional targets of TRIM71, we co-overexpressed Lin28B or HMGA2 with TRIM71 to determine whether Lin28B or HMGA2 overexpression overcomes the inhibitory effect of TRIM71 on tumorigenic phenotypes (proliferation and invasion) of cancer cells." (PMID 27821801, 2016). "Altogether, our work uncovers a novel role for TRIM71 in non-canonical NMD, specifically targeting PTC-lacking mRNAs for NMD/UPF1-mediated decay, and it sheds further light on the RNA recognition and repression mechanisms of this stem cell-/cancer-specific protein." (PMID 31732746, 2019).
tumor (14 papers, 2015 to 2025). "To explore the mechanism underlying the tumor-promoting effects of TRIM71, we transfected with siRNAs targeting TRIM71 and performed RNA-seq." (PMID 39267787, 2024). "Although TRIM71 has been shown to promote proliferation in a variety of cells, the relationship between TRIM71 and tumor biology and the associated molecular mechanisms are still unclear." (PMID 29541383, 2018). "Furthermore, based on the OncoVar online database, TRIM16, TRIM59, TRIM62, and TRIM71 genes were shown to act as tumor mutation drivers." (PMID 35873464, 2022). "We firstly analyzed the correlation between the expression of TRIM71 and tumor stem cell markers in HCC and HB and found significant positive correlation between TRIM71 and CD133, CD24, EPCAM, and LGR5 in HCC and HB tumor samples." (PMID 39267787, 2024). "For example, compared to non-tumor tissue, TRIM71 is upregulated and RBFOX3 is downregulated in tumor tissue." (PMID 33854615, 2021). "The results showed higher tripartite motif containing 71 [TRIM71] expression in BLCA tissues compared to that in non-tumour tissues, while DARS2 and RBMS3 expression levels were downregulated in tumour tissues." (PMID 33685397, 2021). "A novel lncRNA LINK-A has been found to suppress tumor antigenicity and immune–related tumor suppression through signaling related to TRIM71 in triple-negative breast cancer (TNBC)." (PMID 33126510, 2020). "Conversely, TRIM71 depletion remarkably promoted tumor growth, consequently leading to increased tumor weight and mass compared with the control group." (PMID 31570706, 2019). "In agreement with the cell-based results, overexpression of TRIM71 significantly repressed tumor growth in vivo compared with the control group as indicated by the tumor volumes." (PMID 31570706, 2019). "On the basis of the observed relationship between tumor size and TRIM71 expression in clinical cases and the functions of TRIM71 in NSCLC cell proliferation, we explored the specific molecular biological mechanisms associated with these effects." (PMID 29541383, 2018). "In this study, we found that TRIM71 protein levels are correlated with a range of clinicopathological parameters such as tumor size, differentiation, lymph node metastasis, TNM staging, and prognosis." (PMID 29541383, 2018). "We found that TRIM71 protein levels were higher in tumor cell lines than in HBE normal bronchial epithelial cells." (PMID 29541383, 2018). "Subsequent colony-formation assays showed positive correlations between TRIM71 expression and the colony-formation ability of tumor cells." (PMID 29541383, 2018). "The RNA-binding protein Lin28B, an important substrate of TRIM71-mediated ubiquitination, negatively regulates the biogenesis of the tumor-suppressive let-7 family at the post-transcriptional level." (PMID 27821801, 2016). "TRIM71 suppressed cellular transformation and tumor formation by directly inhibiting the activity of the oncoprotein, Lin28B." (PMID 27821801, 2016). "To establish a functional role of TRIM71 in Lin28B-mediated cellular transformation and tumor formation, we directly injected NIH/3T3 cells used in soft agar colony-formation assay into nude mice and compared their abilities to form tumors." (PMID 27821801, 2016). "Invasion assays revealed that TRIM71 knockdown also increased cell invasion compared with control cells, suggesting that TRIM71 is required for tumor invasion." (PMID 27821801, 2016). "Overexpression of Lin28B alone significantly enhanced tumor formation, whereas co-expression of Lin28B and TRIM71 markedly inhibited tumor growth." (PMID 27821801, 2016).
tumor (continued). "TRIM71 overexpression opposed Lin28B-induced transformation in primary cells and inhibited tumor formation in a mouse model." (PMID 27821801, 2016). "The increase in proliferation and invasion induced by depletion of TRIM71 demonstrated that TRIM71 has a potential tumor-suppressive role." (PMID 27821801, 2016). "Since TRIM71 inhibits tumor growth initiated by Lin28B, we examined the function of TRIM71 in suppressing tumorigenic phenotypes." (PMID 27821801, 2016). "Additionally, silencing of TRIM71 significantly inhibited the tumorigenic ability and reduced the tumor weight and tumor volume of HuH-7 cells in an in vivo xenograft mouse model." (PMID 39267787, 2024). "Interestingly, in tumor tissues from mice models of hydrodynamic tail-vein injection induced by TRIM71, oncofetal-like ecological characteristics are activated, along with the upregulation of key serine/glycine regulatory genes Psph and Psat1." (PMID 39267787, 2024). "Furthermore, TRIM71 was sequentially upregulated as tumor grade increased, whereas the expression remained little difference between early and late tumor stage, supporting the potential function of TRIM71 in the initiation of less differentiated liver tumor." (PMID 39267787, 2024). "Thus, LINK-A acted to attenuate intrinsic tumor suppressor barriers via the GPCR/PKA/TRIM71 signaling cascade, forming a resistance strategy for immunological cancer escape." (PMID 37767098, 2023). "In addition, the TRIM71-overexpressed tumor samples exhibited strikingly reduced Ki-67 signals, indicating retarded proliferation of these tumor cells." (PMID 31570706, 2019). "Accordingly, the tumor weight and mass were significantly reduced upon TRIM71 overexpression." (PMID 31570706, 2019). "In tumor tissues, TRIM71 protein levels were generally higher than that in adjacent lung tissues." (PMID 29541383, 2018). "Importantly, TRIM71 expression was found to be positively correlated with clinicopathological parameters, including differentiation (p = 0.016), tumor size (p < 0.0001), lymph node metastasis (p = 0.007), and pathological TNM stage (p = 0.01)." (PMID 29541383, 2018). "Notably, the differences in TRIM71 protein expression between tumor tissues and adjacent lung tissues were statistically significant (p < 0.0001)." (PMID 29541383, 2018). "Notably, TRIM71 mRNA levels were significantly lower in tumor samples of cervical, head and neck, ovary, stomach, and kidney origin." (PMID 27821801, 2016). "Specifically, genes such as TRIM71, DBH, HP, FER1L4, and GCH1 exhibited dynamic and progressive expression changes along tumor grades, with significant increases in Grade 4 tumors compared to Grade 1 (Wilcoxon test, adj." (PMID 41347690, 2025). "We also tested the reported TRIM71 target CDKN1A/p21, a classic tumor suppressor, and found that knockdown of TRIM71 elevated CDKN1A mRNA levels and protein levels." (PMID 39267787, 2024). "Studies have shown that TRIM71 can inhibit the expression of tumor suppressor CDKN1A/p21 and promote the proliferation of tumor cells." (PMID 33854615, 2021). "A pathological TRIM71 upregulation has been observed in 50% of HCC patients and is correlated with advanced tumor stages and poor prognosis." (PMID 31732746, 2019). "Our data shows that TRIM71 represses the mRNA of the cell cycle inhibitor and tumor suppressor CDKN1A/p21 and promotes the proliferation of HepG2 tumor cells." (PMID 31732746, 2019). "Thus, strong TRIM71 activity potentially suppresses cellular transformation driven by Lin28B-let-7 in tumors in which this pathway is conserved by attenuating Lin28B protein function, thereby inhibiting tumor cell growth through inhibition of potential let-7 target oncogenes, especially HMGA2." (PMID 27821801, 2016). "Taken together, these data indicate that TRIM71 acts through post-transcriptional repression of Lin28B and subsequent modulation of let-7-HMGA2 signaling during tumorigenesis to potentially function as a tumor suppressor." (PMID 27821801, 2016).
infection (2 papers, 2013 to 2025). The state of being infected such as from the introduction of a foreign agent such as serum, vaccine, antigenic substance or organism. "Substantiating this observation, post-IAV-infection, there was a significant decrease in TRIM71 and IFNAR2 protein levels." (PMID 40219968, 2025).
TRIM71 also shares sentences with these, for which no sentence is quoted: teratoma (3 papers); breast carcinoma (2); limb-girdle muscular dystrophy type 2H (2); adenocarcinoma (1); Azoospermia (1); brain tumor (1); colorectal carcinoma (1); muscular atrophy (1); myopathy (1); neurodevelopmental disorder (1); prostate carcinoma (1); testicular germ cell tumor (1); testicular teratoma (1).